NUTM1 (NUT midline carcinoma family member 1)
Description:
Plays a role in the regulation of proliferation. Regulates TERT expression by modulating SP1 binding to TERT promoter binding sites.
Synonyms: C15orf55; NUT; DKFZp434O192; FAM22H
Tractability: PROTAC: ubiquitination databases record sites on it.
Gene: Protein-coding gene on chromosome 15 (34,343,315 to 34,357,737, forward strand). Ensembl gene ENSG00000184507.
Subcellular location: Cytoplasm; Nucleus
Gene Ontology:
Molecular function: protein binding
Cellular component: cytoplasm; nucleus
Genetic constraint (gnomAD): Loss-of-function variants: 35 observed, 87.41 expected, observed/expected ratio (o/e) 0.4, 90% interval 0.31 to 0.53. The upper end of that interval is the gene's LOEUF score, 0.53, which puts it in group 2 of 6, group 1 being the genes least tolerant of losing a copy. Missense variants: 1,318 observed, 1,456.1 expected, observed/expected ratio (o/e) 0.91, 90% interval 0.86 to 0.95. Synonymous variants: 487 observed, 557.06 expected, observed/expected ratio (o/e) 0.87, 90% interval 0.81 to 0.94.
Homologues: Orthologues: chimpanzee NUTM1 (98% identical), macaque NUTM1 (91% identical), pig NUTM1 (70% identical), rabbit NUTM1 (66% identical), rat Nutm1 (65% identical), mouse Nutm1 (64% identical), guinea pig NUTM1 (60% identical), dog NUTM1 (57% identical). Paralogues in human: NUTM2A (31% identical), NUTM2B (31% identical), NUTM2D (31% identical), NUTM2E (31% identical), NUTM2F (31% identical), NUTM2G (31% identical).
Diseases named in the same sentence as NUTM1 in open-access papers:
NUTM1 is named in the same sentence as 95 diseases in open-access papers, as found by Europe PMC text mining. Sharing a sentence is not in itself a finding about the gene and the disease. The quoted sentences say what the papers report.
NUT carcinoma (103 papers, 2013 to 2026). "The questionnaire assessed self-reported awareness across five domains (clinical manifestations, diagnostic approaches, treatment, prognosis, and common NUTM1 fusion partners) and awareness of NUT carcinoma–related organizations." (PMID 41772604, 2026). "We believe that the 18F-FDG PET/CT features of NUTM1-rearranged lung sarcoma resemble those of NUT carcinoma and SMARCA4-deficient NSCLC." (PMID 41001035, 2025). "Another novel entity with a very poor prognosis is NUT carcinoma, composed of undifferentiated primitive cells with irregular overlapping nuclei with prominent nucleoli and defined by pathogenic fusions of the NUTM1 gene, most commonly NUTM1::BRD4." (PMID 38085333, 2024). "About 70% of NUT carcinoma is associated with chromosome translocation events that lead to the formation of a BRD4::NUTM1 fusion gene." (PMID 38724194, 2024). "Although NUT carcinomas are rare variants of squamous carcinoma, which harbor fusions on the NUTM1 gene on 15q14 chromosome, they more often reside in the upper respiratory and gastrointestinal tract and mediastinum." (PMID 37627947, 2023). "The genetic hallmark of NUT carcinomas is a translocation of the NUTM1 [formerly known as NUT (nuclear protein in testis) gene]." (PMID 35957893, 2022). "NUT carcinoma is a rare and highly aggressive epithelial malignancy characterised by chromosomal rearrangements involving NUTM1." (PMID 41541495, 2026). "NUT carcinoma (NC) is an aggressive malignancy driven by BRD4::NUTM1 and other NUTM1 fusion oncogenes." (PMID 41266112, 2026). "BACKGROUND: NUT carcinoma is a rare and highly aggressive malignancy defined by NUTM1 gene rearrangement and is frequently misdiagnosed because of non-specific clinicopathological features." (PMID 41772604, 2026). "Characterized by rearrangements of the NUTM1 gene, NUT carcinoma most commonly arises when the NUTM1 gene fuses to the BRD4 transcriptional activator." (PMID 41194824, 2025). "NUT carcinoma (NC) is a highly aggressive malignancy characterized by an oncogenic fusion gene incorporating the NUTM1 gene." (PMID 41190236, 2025). "Routine use of agnostic molecular investigations, including whole genome sequencing, identified a chromosome 15:19 translocation, with BRD4::NUTM1 gene fusion on RNA sequencing, confirming NUT carcinoma." (PMID 40277298, 2025). "Nuclear protein in testis (NUT) carcinoma is an aggressive subtype of squamous cell carcinoma arising from a chromosomal translocation involving the NUTm1 gene." (PMID 40370864, 2025). "Nuclear protein in testis (NUT) carcinoma is a rare and aggressive cancer arising from genetic rearrangements of the NUTm1 gene." (PMID 40370864, 2025). "In particular, the NUTM1-rearranged (NUTM1-immunopositive) cases should be distinguished from the more aggressive NUT carcinoma, as both share overlapping anatomic sites and squamous cell phenotype and express NUTM1." (PMID 41350449, 2025). "These included a possible translocation between NUTM1 on chromosome 15q and a region on chromosome 19p upstream of BRD4 and a possible BRD4-NUTM1 fusion in two patients (one with NUT carcinoma and another with porocarcinoma)." (PMID 39847581, 2025). "First described in the 1990s, NUT carcinomas are poorly differentiated carcinomas defined by the presence of chromosomal rearrangements in the NUTM1 gene on chromosome 15q14." (PMID 39839761, 2024). "The characteristic genetic change of NUT carcinoma is the rearrangement of NUT middle carcinoma family member 1 (NUTM1) gene." (PMID 39026498, 2024). "NUT carcinoma is characterized by translocations involving the NUTM1 gene (located on chromosome 15q14) and its fusion with other partner genes." (PMID 40336973, 2024). "BRD4::NUTM1 has been shown to drive overexpression of SOX2 in NUT carcinoma cells, which induces an aberrant stem cell-like growth feature." (PMID 38315310, 2024).
NUT carcinoma (continued). "NUT carcinoma is genetically characterized by a rearrangement of the NUTM1 gene (Nuclear Protein in Testis) on chromosome 15q14." (PMID 38491228, 2024). "The NSD3::NUTM1 fusion is reported exclusively in NUT carcinoma, an aggressive cancer typically characterized by epithelial differentiation and considered a subtype of squamous cell carcinoma." (PMID 39200173, 2024). "NUT carcinoma (NC) is an extremely rare, aggressive malignancy characterized by chromosomal rearrangements in the NUTM1 (nuclear protein in testis) gene." (PMID 39839761, 2024). "Treatments, especially for NUT carcinoma, have been undergoing development during the last decades; however, these drugs mostly target genes fused to NUTM1 in cancer; for example, BET inhibitors target BRD4 in the BRD4-NUTM1 fusion protein." (PMID 39013578, 2024). "Among NUT carcinoma, BRD4:NUTM1 was the most common variant and only one case harbored BRD3:NUTM1 rearrangement." (PMID 36937407, 2023). "NUT carcinoma is driven by NUTM1 gene rearrangements, and NUT protein immunohistochemistry is useful to highlight this genetic aberrancy—as NUT protein expression is not normally seen in cells outside of the testis and ciliary ganglion." (PMID 36941503, 2023). "The karyotype of NUT carcinomas is usually simple, with the only aberration being the rearrangement involving the NUTM1 gene." (PMID 38067300, 2023). "Nuclear protein in testis (NUT) carcinoma (NC) is a rare, aggressive tumor with a typical NUTM1 gene rearrangement." (PMID 38239638, 2023). "NUT carcinoma (NC) is a rare but very aggressive subtype of squamous carcinoma harboring the characteristic genetic rearrangement involving the NUTM1 gene." (PMID 37049806, 2023). "Gene fusions involving the NUTM1 gene are also found in thymic tumors, specifically in NUT carcinomas, which are considered a subtype of thymic carcinomas." (PMID 38067300, 2023). "NUT carcinoma is a poorly differentiated carcinoma which is defined by a rearrangement of the nuclear protein in testis (NUTM1) gene on chromosome 15q14." (PMID 35326613, 2022). "NUT carcinoma is defined by the presence of a NUTM1 (15q14) rearrangement with multiple other genes." (PMID 35372003, 2022). "NUT carcinoma (nuclear protein in testis carcinoma, NC), formerly known as NUT midline carcinoma, is a poorly differentiated and highly aggressive tumor which is molecularly defined by an aberrant NUTM1 fusion gene." (PMID 36387105, 2022). "The function of NUTM1 fusion genes was primarily characterized in NUT carcinoma with BRD4-NUT fusion." (PMID 34898574, 2021). "The development of the highly specific monoclonal C52 antibody, which features an approximately 87% sensitivity and 100% specificity, has revolutionized the diagnosis of NUT carcinoma and NUTM1-rearranged tumors." (PMID 34898574, 2021). "The distinction between NUTM1-rearranged poroid tumor and NUT carcinoma has a profound impact on a patient’s treatment and prognosis." (PMID 34898574, 2021). "It is also important to note that a subset of poroid adnexal skin tumors, including poroma and porocarcinoma, harbors NUTM1-rearrangement and should be excluded before a diagnosis of NUT carcinoma is made on a skin-based tumor." (PMID 34898574, 2021). "NUT carcinoma is another rare, highly aggressive neoplasm with predilection for the midline, defined by recurrent NUTM1 fusions." (PMID 33891143, 2021). "NUT midline carcinoma, renamed NUT carcinoma (NC), is an aggressive squamous cancer defined by rearrangement of the NUTM1 gene." (PMID 32328562, 2020). "For example, translocation of BRD-containing BRD4 to NUTM1 in human cells generates an oncoprotein that drives a rare and aggressive form of squamous cell carcinoma, NUT midline carcinoma (NMC)." (PMID 32695779, 2020). "NUT midline carcinoma is an aggressive neoplasm defined by chromosomal rearrangements of the nuclear protein in testis (NUT) gene (NUTM1)." (PMID 32588132, 2020).
NUT carcinoma (continued). "NUT carcinoma is defined by a gene rearrangement between the NUT (NUTM1) gene on chromosome 15q14 and one of the other partner genes." (PMID 29538329, 2018). "NUT carcinoma (NC) is a rare, yet aggressive disease (median survival of 6.5 months) of the young defined by a translocation of the nuclear protein in testis gene 1 (NUTM1)." (PMID 41766922, 2026). "The initial postoperative histopathological evaluation suggested undifferentiated endometrial sarcoma; however, subsequent immunohistochemical (IHC) analysis and fluorescence in situ hybridization revealed NUTM1 rearrangement, confirming the diagnosis of NUT carcinoma." (PMID 41590214, 2026). "Some fusion partners of NUTM1 seem to have a prognostic impact in NUT carcinoma patients." (PMID 39863772, 2025). "NUT carcinoma is molecularly characterized by an aberrant NUTM1 fusion gene on chromosome 156." (PMID 39863772, 2025). "NUT carcinoma is genetically characterized by rearrangement of NUTM1 gene on 15q14." (PMID 38217715, 2024). "In addition, Western blotting analysis confirmed the correct size of the BRD4::NUTM1 fusion protein in mouse NUT carcinomas (mNCs)." (PMID 38724194, 2024). "In the mediastinum NUTM1 rearrangements are primarily seen in NUT carcinomas." (PMID 38067300, 2023). "NUTM1 (also known as NUT) gene rearrangement could lead to NUT carcinoma (NC), which is an aggressive subtype of squamous cell carcinoma." (PMID 38130463, 2023). "Finally, case 421 is a classic example of a patient with squamous cell features, where the identification of NUTM1 fusion is pathognomonic for NUT carcinoma." (PMID 36933203, 2023). "However, an external histopathological consultation accompanied by molecular work-up with the detection of a NSD3::NUTM1 fusion, yielded the unexpected diagnosis of a sinonasal NUT carcinoma originating from the maxillary sinus." (PMID 37118352, 2023). "Although several NUTM1 translocations have been found to be associated with NUT carcinoma, to the best of our knowledge, up to this day there is no known specific etiology for the NUTM1 translocation." (PMID 35372003, 2022). "NUT carcinoma (NC) is an aggressive and poorly differentiated squamous cell cancer driven by BRD4::NUTM1 and other NUTM1 fusion oncogenes." (PMID 41266112, 2026). "NUT carcinoma (NC) is a rare exceptionally aggressive malignancy, defined by NUTM1 gene translocations, most commonly generating a BRD4::NUTM1 fusion that results in a poor prognosis and limited therapeutic options." (PMID 41754610, 2026). "NUT carcinoma (NC) is an aggressive solid tumor driven by the BRD4::NUTM1 and other NUTM1 fusion genes." (PMID 41266112, 2026). "Although NUTM1 can fuse to numerous different partner genes, it most frequently forms a BRD4-NUTM1 fusion oncogene related to NUT carcinoma." (PMID 39711966, 2024). "NUT carcinoma (NC) is a rare and aggressive subtype of squamous carcinoma characterized by genetic rearrangements involving the NUTM1 (NUT midline carcinoma family member 1) gene." (PMID 35957893, 2022). "In previous studies, common partner BRD9::NUTM1 was indicated in BCP-ALL, while BRD4::NUTM1 was reported in nut midline carcinoma." (PMID 35269896, 2022). "NUT carcinoma (or NUT midline carcinoma) is a rare and aggressive subtype of epithelial carcinoma, defined by the evidence of NUT gene (NUTM1) rearrangement." (PMID 36046116, 2021). "Chromosomal rearrangement of the Nuclear protein in testis (NUTM1, aka NUT) gene defines a rare subtype of squamous cell carcinoma termed NUT carcinoma (NC, also known as NUT midline carcinoma [NMC])." (PMID 32328562, 2020). "NUT carcinoma depends on the BRD4::NUTM1 fusion, which current inhibitors can target but without durable clinical efficacy." (PMID 41190236, 2025). "We included 61 studies with 278 SNCs including 25 IDH2-mutant, 41 NUT carcinoma, 187 SWI/SNF loss, and 25 triple negative SNCs (without IDH2 mutation, NUTM1 rearrangement, and SWI/SNF inactivation) for analyses." (PMID 36937407, 2023).
NUT carcinoma (continued). "NUT carcinoma (NC), formerly known as NUT midline carcinoma (NMC), is a rare but very aggressive tumor, genetically defined by a reciprocal translocation involving the NUTM1 (formerly known as NUT (nuclear protein in testis)) gene." (PMID 35681742, 2022). "It is noteworthy that gene fusions involving NUTM1 are not restricted to NUT carcinoma." (PMID 40336973, 2024). "While morphologic features were still consistent with nasopharyngeal carcinoma, pertinent negative staining with NUTM1 could further disprove the mentioned NUT carcinoma." (PMID 38962102, 2024). "Notably, patients with NUT carcinoma in the head and neck region and who exhibit the NSD3::NUTM1 fusion tend to have a notably improved prognosis compared to the typical NUT carcinoma median survival of 6.5 months, with a median overall survival of 36.5 months." (PMID 39200173, 2024). "Besides NUTM1 rearrangements, no other molecular alterations have been reported in NUT carcinomas." (PMID 38067300, 2023).
squamous cell carcinoma (28 papers, 2012 to 2026). A carcinoma arising from squamous epithelial cells. "Translocations of BRD4 (and more rarely BRD3) to the NUTM1 (NUT midline carcinoma family member 1) gene cause a rare but aggressive form of squamous cell carcinoma." (PMID 30554943, 2019). "BRD4::NUTM1 aberrantly activates transcription factors (TFs) associated with basal progenitor cells of stratified epithelium, resulting in a poorly differentiated squamous cell carcinoma (SCC) phenotypes." (PMID 41266112, 2026). "Histologically, these NUTM1::bromodomain complex gene fusion tumors comprise a poorly differentiated or undifferentiated squamous carcinoma (SC), and approximately 33% exhibit mature squamous differentiation described as commonly “abrupt”." (PMID 34997561, 2022). "NUT midline carcinoma (NMC), a rare type of squamous cell carcinoma, is genetically characterised by NUT midline carcinoma family member 1 (NUTM1) gene rearrangement." (PMID 32650830, 2020). "NUT midline carcinoma (NMC) is a rare, highly aggressive, and poorly differentiated squamous cell carcinoma genetically characterised by a NUT midline carcinoma family member 1 (NUTM1) gene rearrangement on chromosomal 15q14." (PMID 32650830, 2020). "NC is a rare and aggressive subtype of poorly differentiated squamous carcinoma, genetically defined by the rearrangement of the NUT (recently renamed NUTM1) gene." (PMID 36431263, 2022). "Notably, in NUT midline carcinoma, a highly aggressive squamous cell carcinoma characterized by rearrangements of the NUT/NUTM1 gene, a novel NSD3-NUT fusion oncogene has been identified." (PMID 41301842, 2025).